TNF (tumor necrosis factor)
Diseases named in the same sentence as TNF in open-access papers (continued):
Sharing a sentence is not in itself a finding about the gene and the disease.
tumor (continued). "TNF plays a role in both tumor angiogenesis and cell death, promoting the progression and metastasis of tumors." (PMID 39450262, 2024). "This can be explained by the fact that TNF-α is a potent immunostimulatory cytokine with local effects in the tumor microenvironment and possible systemic effects; it can also contribute to the maintenance of a pro-inflammatory environment." (PMID 39408920, 2024). "TNF-α, on the other hand, has a dual role in tumor progression by not only promoting inflammation but also inducing apoptosis in tumor cells." (PMID 39456637, 2024). "We found that RA-TEXs amplified TNF-α expression to different extents, with the 6Gy*3f group demonstrating a significant, over three-fold increase in tumor-specific TNF-α." (PMID 39772073, 2024). "M1 macrophages, induced by interferon-gamma (IFN-γ) and lipopolysaccharide (LPS), are pro-inflammatory and exhibit anti-tumor properties, marked by the production of IL-12, tumor necrosis factor-alpha (TNF-α), and inducible nitric oxide synthase (iNOS)." (PMID 39795180, 2024). "TCR135 specifically recognized APC-presented EBNA1 and mediated the indirect killing of HLA II–negative tumor cells in a TNF-α–dependent manner." (PMID 38412034, 2024). "TNFα has different effects in different tumors, which promotes tumor examples in some tumors, inhibits tumor progression in others, and even plays a dual role 31-33." (PMID 39664565, 2024). "It has also been shown that anti-folate receptor-α IgE reprograms and recruits macrophages in the tumor microenvironment to attack tumors via TNF-α/CCL2 signaling." (PMID 39596024, 2024). "TNF-mediated nuclear factor kappa-B signaling exerts inhibitory effects on tumor cells or enhances the migration and infiltration of activated immune cells, working alongside IFN-γ to achieve anti-tumor effects." (PMID 39538305, 2024). "These hypofunctional T cells with elevated expression of inhibitory receptors fail to produce IFN-γ, TNF-α, granzyme B, and perforin to eliminate tumor cells." (PMID 38321486, 2024). "Molecularly, EMT leads to the epigenetic and transcriptional silencing of interferon regulatory factor 6 (Irf6), rendering tumor cells less sensitive to the pro-apoptotic effects of TNF-α." (PMID 38378697, 2024). "On the other hand, and in line with our findings, in mCRPC TNFα has demonstrated to have an anti-tumour activity, by being effective in destroying tumour vasculature and stimulating anti-tumour immunity." (PMID 39239510, 2024). "Tumor-infiltrating lymphocytes and other immune effectors secrete cytokines such as TNFα and IFNγ, which can activate NFκB and STAT1 signaling in cancer cells." (PMID 39461475, 2024). "The results showed that the primary tumor microenvironment was significantly enriched with various tumor-related pathways, such as TNFα/NFκB-signaling and IL6-JAK-STAT3-signaling." (PMID 39323622, 2024). "These cells produce pro-inflammatory cytokines (of particular interest are TNF-α, IL-6, and interferon), proteases, MMPs, and NETs that support inflammation and favor tumor development and metastasis." (PMID 38612841, 2024). "This process recruits more T lymphocytes to infiltrate the tumor lesion and releases immunogenic factors (such as TNF, IL-1, HMGB1, etc.)to indirectly stimulate the immune system, exerting an immunological killing effect." (PMID 38762484, 2024). "Ji and colleagues illustrated the significance of neutralizing TNF-α levels in the tumor microenvironment to enhance chemotherapy response, with promising clinical implications." (PMID 38341580, 2024). "Endogenous secretion of TNF-α by TAMs and tumor cells induce EMT by inhibiting epithelial marker E-cadherin transcription and upregulating mesenchymal markers N-cadherin, fibronectin, and vimentin expression." (PMID 38935134, 2024).
tumor (continued). "To assess the extent of activation, we measured the concentration of released effector cytokines, interferon (IFN)-γ, tumor necrosis factor (TNF) and interleukin (IL)-2, in the culture medium after the engagement of tumor cells by the T cells." (PMID 39510795, 2024). "We next explored TNFα as a potential cytotoxic mediator shaping tumour evolution and the role of PGLYRP1 in regulating/counteracting this effect." (PMID 38754953, 2024). "Cytotoxic CD8+ T cells play a critical role in eliminating tumor cells by producing Granzyme B (GzmB) and effector cytokines such as IL-2, TNF-α, and IFN-γ." (PMID 38750022, 2024). "Eosinophils also have anti-tumour effects via the secretion of various substances (TNF-α, granzyme, cationic proteins, and IL-18)." (PMID 38673958, 2024). "In the case of TNF, vinyl chloride increased the mRNA and protein activity, indicating potential impact in tumor microenvironment." (PMID 38982523, 2024). "Increased TNF-α stimulates macrophage activation, which enhances their function of killing tumor cells." (PMID 38886454, 2024). "Previous reviews, primarily comprising cell line studies, have suggested that TNF-α promotes invasive and malignant behaviour in BC cells, contributing to tumour growth, progression, and metastasis." (PMID 39342063, 2024). "At early stages of tumor progression, inflammatory macrophages are stimulated by KRAS‐mutated acinar cells to release proinflammatory cytokines, including TNF‐α and IL‐6." (PMID 38411356, 2024). "TNF-α can have dichotomous effects on tumor growth and survival via canonical signaling through its 2 receptors, TNFR1 and TNFR2." (PMID 38912584, 2024). "Once activated, CD8 T lymphocytes release IFN-γ, IL-2, and TNF-α, crucial cytokines for the differentiation of T cells into CTLs, which are responsible for the direct destruction of tumor cells." (PMID 39682686, 2024). "mAb can participate in the innate immune response through immune cells (killer cells) and humoral immune molecules (complement); therefore, it can produce pro-inflammatory cytokines, especially TNF-α, which together induce apoptosis in tumor cells." (PMID 39010088, 2024). "As previously found, TNF-α at the tumor site is primarily derived from M1 macrophages and tumor cells." (PMID 38840908, 2024). "Elevated stress hormones further promote the release of pro-inflammatory cytokines, such as IL-6 and TNF-α, which enhance tumor proliferation and migration." (PMID 39766169, 2024). "In cancer-related pain, TRPV4 channels are directly activated due to the excessive generation of oxidative stress by-products (e.g., H2O2), acidification, and the release of mediators such as TNF-α by the tumor microenvironment." (PMID 38730655, 2024). "In conclusion, recombinant and TAM-derived TNF-α plays a promoting role in the invasion of tumor cells through various signaling pathways." (PMID 39003350, 2024). "TNF is essential to the anti-tumor function of cytotoxic T cells, assisting CAR-T cells in clinical treatment." (PMID 38664743, 2024). "The expression of tumor-promoting genes was higher in macrophages polarized with WT EVs than KO EVs, while the expression of TNF and IL6 was reduced." (PMID 38937789, 2024). "TNF-α is an important proinflammatory factor in the tumor microenvironment of BRCA patients and is primarily secreted by stromal cells, tumor-associated macrophages and cancer cells themselves." (PMID 39440049, 2024). "If the tumor is intrinsically TNFα-sensitive, TNFα will initiate apoptosis and promote PANX1 cleavage." (PMID 38195677, 2024). "IDO1 expression is increased in many human tissues, and it is overexpressed in the majority of cancers (90% of glioma cells) by proinflammatory cytokines, such as IFN-γ and TNF-α, or in response to interaction with tumor-infiltrating T or NK cells." (PMID 38473776, 2024).
tumor (continued). "Elevated intra-tumor levels of TIM-3 have also been associated with the suppression of T-cell responses and reduced production of TNF-α, IFN-γ, and GrzB, especially when co-expressed with TIGIT, CTLA-4, or LAG-3." (PMID 38891056, 2024). "The ability of T cells to express IFN-γ and TNF-α plays an important role in anti-tumor immune response." (PMID 38622609, 2024). "In another study, allogenic immunoglobulin G (IgG) in combination with DC stimuli tumor necrosis factor alpha (TNFα) and aCD40 was delivered twice, two days apart, in two cycles 14-16 days post 4T1 tumor implantation in a mouse model." (PMID 38803496, 2024). "In the anti-tumor activity test, D-mannitol is considered to enhance the phagocytosis of mouse macrophages and promote the release of immune active substances’ tumor necrosis factor-α (TNF-α) and interleukin-6 (IL-6) and improve the immune function of mice." (PMID 38786711, 2024). "The tumor suppressor gene, Von Hippel-Lindau (pVHL), was found to block TNF-α, suggesting a role in preventing tumor growth." (PMID 39830670, 2024). "The ELISA results showed that treatment with PD-L1 inhibitors would promote the secretion of IFN-γ and TNF-α in tumor tissue and in vitro co-culture system." (PMID 38448544, 2024). "This study demonstrated for the first time that nuclear PD-L1, caspase-8, and GSDMC are essential for macrophage-derived TNFα-induced tumor necrosis." (PMID 38877579, 2024). "M1 TAMs promote inflammation by secreting cytokines such as IL-1β, inducible nitric oxide synthase (iNOS), and tumor necrosis factor-alpha (TNF-α), exerting anti-tumor effects across multiple cancers." (PMID 39531417, 2024). "The transferred CTLs pretreated with UA substantially enhanced the IFN‐γ, TNF‐α, IL‐2, and granzyme B‐producing capacity in the tumor, spleen, and lymph node." (PMID 38447147, 2024). "Strikingly, FLI1 deficiency within tumor cells culminated in decreased PD-1 and TIM-3 expression on CD8+ T cell surfaces, concomitant with increased IFN-γ and TNF-α release by CD8+ T cells." (PMID 38816360, 2024). "Due to the significance of TNFα-NF-κB signaling in inflammation and tumor immunity, we next chose to focus on detecting the enriched TNFα-NF-κB signaling genes and the signaling dependent inflammatory genes." (PMID 39638799, 2024). "While the N1 population is tumor-cytotoxic and secretes factors like TNF-α, the N2 population is described as a more tumor-promoting population and expresses Arginase180." (PMID 38450755, 2024). "Such increase in TNFα in tumor bearing mice were significantly decreased on treatment with WFA (p < 0.001)." (PMID 39394174, 2024). "Later studies by the same laboratory showed that pDCs can enhance tumor cell proliferation and invasion in vitro through TNF-α secretion activating nuclear factor-kappaB (NF-κB) and CXCR4 chemokine receptor in tumor cells." (PMID 38468824, 2024). "Rather than mediating an anticancer effector function, this CD8 cell type has been described to promote fibrosis and tumor progression in a NASH mouse model by secreting TNF." (PMID 38226976, 2024). "Briefly, M1 macrophages are considered anti-tumor due to their cytotoxic effect on tumors cells exerted via tumor necrosis factor-α and nitric oxide, whereas M2 macrophages are considered protumorigenic due to their immunosuppressive and angiogenic roles." (PMID 39516662, 2024). "Of note, TNF-related signaling in the Tc and PD-L1/PD-1 checkpoint pathway was increased in TH collected in tumor-sparse regions." (PMID 39001353, 2024). "We found that the JK10 CAR had a stronger IFNγ and TNFα response, as measured in overnight co-culture assays with tumor target cells." (PMID 38203757, 2024). "These cytokines play crucial roles in cancer progression: TNF-α enhances tumor invasiveness and promotes malignant cell survival, while IL-6 acts as a growth factor for malignant cells and activates oncogenic signaling pathways." (PMID 39597645, 2024).
tumor (continued). "Studies have shown that tumor sensitivity to cell death and PANoptosis are related to TNF-α and IFN-γ expression profiles." (PMID 38967843, 2024). "Previous studies have shown that TNF-α enhances tumor metastasis by upregulating the expression of adhesion molecules and stimulating the expression of angiogenesis factors." (PMID 39927118, 2024). "Glucose transporter 1 (GLUT1) inactivation leads to MR for oxidative phosphorylation, generating excess reactive oxygen species (ROS), and accumulated ROS enhances TNF-a-mediated tumor cell death." (PMID 39588377, 2024). "When secreted by M1 macrophages, TNF-α stimulates an inflammatory response, generating reactive species such as superoxide radicals that promote tumor cell destruction and anti-tumor immunity." (PMID 39766056, 2024). "SIRPα-Fc administration resulted in increased amounts of tumor-infiltrating macrophages, enhanced TNF-α production, and a reduction in IL-10 expression." (PMID 39335665, 2024). "Accordingly, anti-TNF antibody treatment significantly increases the anti-tumor effect triggered by anti-PD-1 antibody." (PMID 39136013, 2024). "Second to arise are the inflammatory cytokines and mediators (e.g., IL-1, IFN-γ, and TNF-α) which are induced by the tumor and host immune system interaction." (PMID 38966634, 2024). "Secondly, The release of cytokines, such as IFN-γ, TNF-α, etc., induces tumor cell apoptosis through the interaction with the corresponding receptors on the surface of tumor cells." (PMID 38245520, 2024). "The presence of prostaglandin E2 (PGE2) and tumor necrosis factor (TNF) within the TME led to the conversion of tumor-infiltrating monocytes in interleukin-1β (IL-1β)-expressing TAMs." (PMID 38817612, 2024). "TECs release inflammatory mediators such as ILs and TNF‐α, which further trigger an inflammatory response that affects surrounding tumor and immune cells." (PMID 39629553, 2024). "We previously used Kaede mice to demonstrate that ovariectomy increases the migration of TNF+ T cells and Th17 cells from the gut to the BM, and to establish that tumor bone growth attracts intestinal NK and Th1 cells to the tumor site." (PMID 38530358, 2024). "Tumor-educated neutrophils (TENs) secrete inflammatory factors, including IL-17, IL-23, and TNF-α, which can activate the AKT and p38 pathways in MSCs, mediating their transformation into CAFs." (PMID 39676857, 2024). "These neoplastic cells together with the surrounding stromal cells dramatically secret abundant angiogenic growth factors, like VEGF and TNF, leading to an extensive abnormal vessel growth, tumor progression, and metastasis." (PMID 38543448, 2024). "Cytokines and chemokines, such as VEGFA, TGF-β, and TNF-α, are released by tumor cells, stromal cells, and immune cells, and they regulate PMNs of distant organs, making them suitable for the metastatic growth of cancer cells recruited." (PMID 38590651, 2024). "In various animal cancer models, TNF-α exhibits broad anti-tumor effects by stimulating the immune system, yet it also presents significant toxicity at the same time." (PMID 39411143, 2024). "Intracellular staining (ICS) revealed significantly higher IFN-γ levels or a greater tendency for production of IFN-γ and TNF-α by T cells, especially in tumor-infiltrating T cells derived from Tmed4ΔTreg mice." (PMID 39480507, 2024). "Further, gene set enrichment analysis (GSEA) also displayed several upregulation of the hallmark gene sets related to tumor progression and EGFR-TKI resistance, including epithelial-mesenchymal transition, angiogenesis, hypoxia, and TNF-α signaling via NF-κB." (PMID 39638994, 2024). "The study has showed that CAR-M activated by VEGFR2 generated substantial amounts of TNF-α, inhibiting tumor growth effectively." (PMID 39175095, 2024). "In other cases, tumor cells driven by TNF-α and IL-6 directly affected wasting of skeletal muscle (a process that is also called cancer cachexia)." (PMID 38276543, 2024).
tumor (continued). "When Salmonella damages cancer cells and bacterial components like flagellin and LPS are encountered, the macrophage inflammasome is activated, increasing IL-1β and TNF-α production in the tumor microenvironment." (PMID 39594765, 2024). "In fact, pretreatment of tumor cells with TNF-α increased the expression of CXCR4 at both mRNA and protein levels." (PMID 39609700, 2024). "Here, we analyzed the level of anti-tumor inflammatory cytokines such as IL-2, TNF-α and IFN-γ in the B16-F10 cancer-bearing mice after the treatment with photothermal-immunotherapy by FSGG/siGal-9." (PMID 38366083, 2024). "This enables the tumor to evade immune detection by inhibiting inflammatory cytokines like TNF-α and suppressing MHC II, CD80, and CD86 expression." (PMID 39118076, 2024). "The abundant expression of TNF-α forced tumor cells to develop towards a poorly differentiated and aggressive basal-like phenotype." (PMID 38167055, 2024). "Mechanistically, macrophages secrete TNFα, which activates the NF-κB pathway in tumor cells, leading to p65 nuclear translocation." (PMID 39555068, 2024). "Tumor cells can secrete numerous pro-inflammatory factors such as TNF-α, interferon-gamma (IFN-γ), IL-1 and IL-6, and parathyroid hormone-related protein (PTHrP) that can trigger cancer cachexia." (PMID 39697630, 2024). "Our study also clarified the potential link between PLOD3 and the TNFα/NF-κB signaling pathway in the tumor microenvironment." (PMID 38184566, 2024). "Tumor necrosis factor‐α (TNF‐α), as a key regulator of innate immunity, has a direct killing effect on tumor cells." (PMID 38774946, 2024). "The stimulatory effect of TNF on cancer cells affects the anti-apoptotic cascade through the tumor promotion pathway of TNF, i.e., tumor promotion via activating NF-κB or a PKCα- and AP-1-dependent pathway of cancer cells." (PMID 39765744, 2024). "RT‐qPCR analysis of tumor specimens revealed elevated mRNA expression levels of TNFα and MMP9 in BIPA." (PMID 38739004, 2024). "To test this possibility, we cultured T cell–inflamed Mgat5-KO or EV tumor cells with increasing concentrations of TNF-α, TRAIL, or FasL, and measured cell death." (PMID 38912584, 2024). "TNF-α is a primary factor in immune suppression of tumor cells against T-cells through PD-L-1 stabilization." (PMID 38660299, 2024). "The selection of cytokines was based on their significant role in regulating the tumor microenvironment, including promoting either the Th1 (IL-2RA, IL-12(p40), IL-15, TNF-α, IL-1β, IL-1RA, and IFN-γ) or the Th2 (IL-4, IL-6, IL-8, and IL-10) profile." (PMID 39768997, 2024). "Helichrysetin, an anti-tumor agent, has the ability to effectively suppress cancer progression by preventing TNF-α-mediated NF-κB signaling." (PMID 39834817, 2024). "M1 macrophages are polarized by lipopolysaccharide (LPS), interferon-gamma (IFN-γ), or tumor necrosis factor (TNF), leading to the secretion of pro-inflammatory cytokines and the ability to eliminate microorganisms and tumor cells." (PMID 38894865, 2024). "TNF‐α, a major cytokine playing a critical role in tumor microenvironment interactions, is decreased during Ld therapy, and this level did not change with disease progression." (PMID 39031503, 2024). "NK cell activation markedly increases the amount of IFN-γ and TNF-α released from the cells, reversing tumor cell-mediated immune system suppression." (PMID 38434708, 2024). "TNF-α was identified in the tumor tissues of three patients with postoperative SD and one patient with postoperative PD using IHC staining, and there was no statistically significant disparity in TNF-α levels between the two groups (p = 0.7007)." (PMID 38748269, 2024). "The other genes were found to be involved in numerous signaling pathways which are closely related to tumor development, such as TNF/NF-kappa/Notch/Hippo." (PMID 38356701, 2024).